SPACA6-AS1 (SPACA6 antisense RNA 1)
Synonyms: LINC01129; SPACA6P-AS
Gene: Long non-coding RNA gene on chromosome 19 (51,685,363 to 51,693,456, reverse strand). Ensembl gene ENSG00000269959.
Gene Ontology:
Biological process: miRNA-mediated post-transcriptional gene silencing
Cellular component: RISC complex